HDAC3 (histone deacetylase 3)
Diseases named in the same sentence as HDAC3 in open-access papers (continued):
Sharing a sentence is not in itself a finding about the gene and the disease.
neurodegenerative disease (18 papers, 2013 to 2025). A disorder of the central nervous system characterized by gradual and progressive loss of neural tissue and neurologic function. "HDAC3 has also been shown to promote the progression of neurodegenerative diseases such as Alzheimer's disease, Charcot‐Marie‐Tooth, Parkinson's disease, and Huntington's disease." (PMID 39143689, 2025). "We also discuss the role of HDAC3 and its inhibitors in some chronic cardiovascular, kidney, and neurodegenerative diseases." (PMID 37072432, 2023). "To summarize, HDAC3 can have a strong neurotoxic action on adult neurons in the brain, leading to neurodegenerative diseases, such as HD." (PMID 36358670, 2022). "With reports of HDAC3 binding to three different ataxin proteins, and HDAC3-specific inhibition ameliorating disease in animal models, our study adds to growing evidence for HDAC3 modulation as a target for multiple neurodegenerative diseases." (PMID 24160175, 2013). "Moreover, recent studies indicate that HDAC3 expression promotes neurodegenerative diseases such as PD, AD and HD." (PMID 36358670, 2022). "Therefore, HDAC3 inhibitors (HDAC3Is) are potentially applicable to the treatment of neurodegenerative diseases and the control of drug addiction." (PMID 28106794, 2017). "In particular, class I, II, and III HDACs such as HDAC3, HDAC4/5, and Sirtuin 1(Sirt1), respectively, have been shown to have critical roles in transcription repression during aging and neurodegenerative diseases." (PMID 40662679, 2025). "The interplay between HDACs 1 and 3 in neurodegenerative diseases is well established as well as the interaction between HDAC1 and HDAC3 in neuronal cells [see for example Ref." (PMID 25798128, 2015). "Furthermore, low-molecular compounds, such as Hes1 dimer inhibitors for neural stem cell (NSC) differentiation and histone deacetylase 3 (HDAC3) inhibitors and SIRT2 inhibitors for neurodegenerative diseases, can be used in combination with immunotherapy." (PMID 35214143, 2022). "Histone deacetylase 3 (HDAC3) inhibitors and SIRT2 inhibitors could also be therapeutic agents for neurodegenerative diseases." (PMID 33171799, 2020). "This study implicates HDAC3 and ataxin-7 interaction as a target for therapeutic intervention in SCA7, adding to a growing list of neurodegenerative diseases that may be treated by HDAC inhibitors." (PMID 24160175, 2013).
cardiovascular disease (8 papers, 2014 to 2025). "A growing body of evidence shows that HDAC3 has been linked to a variety of disorders, including cardiovascular disease, cancer, neurodegenerative diseases, inflammatory diseases, and metabolic diseases." (PMID 35656103, 2022). "Due to this discrepancy between observations, additional investigation is necessary to validate the efficacy of HDAC3 inhibition for cardiovascular diseases." (PMID 39050859, 2024). "Targeted inhibition of TRAP1 or enhancement of HDAC3 activity may be an important strategy for treating aging and cardiovascular diseases." (PMID 41403695, 2025). "However, the research done thus far on the role, mechanism, and inhibitors of HDAC3 in cardiovascular diseases is insufficient." (PMID 35656103, 2022). "This work significantly advances the field by establishing HDAC3 — and its phosphorylation state — as a key chromatin-bound regulator of mitochondrial transcription in the aortic valve, offering insights into how HDACs modulate metabolic-epigenetic crosstalk in cardiovascular disease." (PMID 40923319, 2025). "RGFP966 is an inhibitor of histone deacetylase 3 (HDAC3), an important regulator of cardiovascular diseases which was found to be upregulated in atherosclerotic lesions, and can reduce atherosclerotic lesions by inhibiting EndMT in the aortic root." (PMID 34604359, 2021).
metabolic disease (6 papers, 2015 to 2024). A congenital disorder (due to inherited enzyme abnormality) or acquired (due to failure of a metabolically important organ) disorder resulting from an abnormal metabolic process. "In conclusion, HDAC3, NCoR1, and NCoR2 play a major role in regulating metabolism and have been implicated in several metabolic diseases." (PMID 37674539, 2023). "Rev-erbα recruits corepressors nuclear receptor corepressor 1(NCOR1) and histone deacetylase 3 (HDAC3) to inhibit the transcription of genes associated with circadian rhythm and metabolic diseases." (PMID 36874248, 2023). "A comprehensive identification of target genes and pathways regulated by HDAC3 and NCoR1 in the context of inflammation and metabolic diseases is essential for the drug development." (PMID 37674539, 2023). "Is targeting the HDAC3/NCoR1 corepressor complex an effective therapeutic strategy for metabolic diseases?" (PMID 37674539, 2023). "In conclusion, despite significant progress in understanding how HDAC3 and NCoR1 control inflammation in metabolic disorders, there are still various areas that researchers can explore to deepen our knowledge and identify potential therapeutic strategies." (PMID 37674539, 2023). "Further studies are needed to thoroughly understand the mechanisms through which HDAC3, and NCoR1/2 govern metabolic processes and the implications for treating metabolic diseases." (PMID 37674539, 2023). "Understanding the specific mechanisms by which HDAC3 and NCoR1 interact with lipid metabolism genes is essential for unraveling their roles in liver function and exploring potential therapeutic targets for metabolic diseases related to lipid metabolism." (PMID 37674539, 2023). "Additionally, reduced HDAC3 is associated with mitochondrial biogenesis, and HDAC3‐specific deletion in skeletal muscle or class I‐specific inhibitors could be used to understand the role of mitochondrial biogenesis in age‐related muscle atrophy and metabolic disease." (PMID 26290460, 2015).
neurological diseases (6 papers, 2017 to 2025). "In the recent decade, HDAC3 has been reported to be implicated in neurodevelopment and various neurological diseases." (PMID 39744685, 2025). "Overall, our results indicate that correct dosing of HDAC3 inhibitors is of crucial importance if translated to a clinical setting for demyelinating forms of CMT or other neurological disorders." (PMID 35320455, 2022). "Over the past years, a growing body of studies has suggested that HDAC3 may serve as a therapeutic target for a variety of neurological diseases probably by modulating neuroinflammation 49-53." (PMID 39744685, 2025). "Our data provided a hint that HDAC3 inhibitor may be a potential therapeutic target combating microglia activation and inflammatory response in neurological diseases." (PMID 28293439, 2017).
adenocarcinoma (3 papers, 2008 to 2015). A common cancer characterized by the presence of malignant glandular cells. "Elevated levels of HDAC3 protein are found in 92% of the SCC subtype, and more recently high expression of HDAC3 has been shown to correlate with poor prognosis in the adenocarcinoma subtype of NSCLC." (PMID 24212667, 2011). "Strong nuclear HDAC1, HDAC2 and HDAC3 immunoreactivity was seen in most adenocarcinomas." (PMID 18212746, 2008).
kidney disorder (3 papers, 2022 to 2025). A disease involving the kidney. "Inhibition of HDAC3 can exert an anti‐inflammatory effect in various models of kidney disease." (PMID 39143689, 2025). "HDAC3 is indispensable for renal development and plays a pivotal role in various renal diseases." (PMID 39143689, 2025).
bacterial infection (2 papers, 2022 to 2023). "More importantly, mice with macrophage specific knockout of HDAC3 showed more susceptible than control mice to pseudomonas aeruginosa, suggesting the critical role of HDAC3 in host defense against bacterial infection." (PMID 35658939, 2022). "More importantly, macrophage specific HDAC3 knockout mice were impaired in host defense against bacterial infection." (PMID 35658939, 2022). "Our studies uncovered important roles of HDAC3 in the regulation of cathepsin-mediated lysosomal degradation and RIP1-mediated inflammatory response in macrophages as well as in host defense against bacterial infection." (PMID 35658939, 2022).
immune diseases (2 papers, 2019 to 2020). "Our findings may therefore be important in establishing HDAC3 as therapeutic target to reduce macrophage cytokine production in the inflamed tissues and inflammatory insults in immune disorders." (PMID 33123128, 2020).
liver (2 papers, 2008 to 2023). "Importantly, we also show that knocking down Yap in Hdac3-LKO mice ameliorates both iron overload and ferroptosis-induced liver injury." (PMID 38034086, 2023).
brain disorder (1 paper, 2015). A disease affecting the brain or part of the brain. "Therefore, future therapeutic intervention(s) to modulate PGK1 activity via HDAC3-mediated deacetylation may serve as a potential target for treating related diseases, such as hemolytic anemia and brain disorders associated with PGK1 dysregulation." (PMID 26356530, 2015).
vasculopathy (1 paper, 2021). "Consistent with the observations in vitro, Nrf2 in the aortic endothelium was required for HDAC3 inhibition-mediated attenuation of T2DM-induced oxidative stress, inflammation, and vasculopathy." (PMID 33736642, 2021).
HDAC3 also shares sentences with these, for which no sentence is quoted: chronic obstructive pulmonary disease (4 papers); multiple sclerosis (4); pancreatic ductal adenocarcinoma (4); fibrosis (3); idiopathic pulmonary fibrosis (3); injury (3); Parkinson disease (3); brain tumor (2); chronic myelogenous leukemia (2); cutaneous squamous cell carcinoma (2); Ewing sarcoma (2); hepatoblastoma (2); inflammation (2); lupus (2); Ovarian Tumor (2); prostate tumors (2); Ureteral obstruction (2); ventricular septal defect (2); acute lung injury (1); acute myocardial infarction (1); acute respiratory distress syndrome (1); Adamantinomatous Craniopharyngioma (1); alcoholism (1); allergic asthma (1); allergic rhinitis (1); allergies (1); atherosclerotic heart disease (1); autism spectrum disorder (1); benign tumors (1); bladder tumors (1).
A further 59 diseases each share a sentence with HDAC3 in 1 paper.